GLP1R (glucagon like peptide 1 receptor)
Diseases named in the same sentence as GLP1R in open-access papers (continued):
Sharing a sentence is not in itself a finding about the gene and the disease.
tumor (continued). "The median diameter of GLP-1R-negative tumours was significantly larger, 38 (range 15–60) mm, compared to 14 (range 5–40) mm in GLP-1R-positive tumours, p = 0.004." (PMID 37894845, 2023). "A possible direct effect of liraglutide in the modulation of testicular function cannot be excluded, this being supported by the recent identification of GLP1R in healthy (non-tumor) human Leydig cells." (PMID 36675601, 2023). "It was elucidated that the exposure of tumor cells to Ex-4 has the potential to confine tumor mass via engaging GLP-1R signaling pathway." (PMID 35620334, 2022). "A recent study suggested that the GLP-1R agonist exenatide promoted apoptosis in Ishikawa cells and attenuated xenograft tumor growth in a mouse model." (PMID 29907137, 2018). "Non-invasive imaging of the β-cell-specific glucagon-like peptide receptor-1 (GLP-1R) would allow the assessment of both β-cell mass and derived tumours, potentially improving the diagnosis of various conditions." (PMID 25006548, 2014). "Biodistribution in CD1 nu/nu mice with a subcutaneous CHL-GLP-1-receptor-positive tumour showed specific uptake in tumour and GLP-1-receptor-positive tissue as well as high non-GLP-1R-mediated kidney absorption for all three peptides." (PMID 25006548, 2014). "In vivo biodistribution of 68Ga-labelled peptides was investigated in CD1 nu/nu mice with subcutaneous CHL-GLP-1R positive tumours; the specificity of the binding to GLP-1R was determined by pre-injecting excess peptide." (PMID 25006548, 2014). "In conclusion, 68Ga-Ex4NOD12, 68Ga-Ex4NOD40 and, to a lesser extent, 68Ga-Ex4NOD27 show comparable results and demonstrate good properties for pancreatic β-cell imaging, as they show high uptake and retention in GLP-1R-positive tumour and tissue." (PMID 25006548, 2014). "The GLP-1R expression has been systematically assessed in a broad spectrum of original human tumor tissues using in vitro receptor autoradiography." (PMID 23230431, 2012). "This discovery lead to an extensive evaluation of the potential of the GLP-1R for targeted tumor imaging and therapy analogous to somatostatin receptor targeting of gut neuroendocrine tumors." (PMID 23230431, 2012). "Third, the tumor-to-background ratio was very high (between 13.6 and 299), substantiating the high potential of this radiopeptide to specifically localize GLP-1R positive lesions within the pancreas." (PMID 23230431, 2012). "Therefore, GLP-1R+ tumor cell staining was always found with GLP-1R+ TME, but some tumors had only TME staining." (PMID 41542041, 2026). "Thus, GLP-1R was detected in both tumor cells and TME cells in TNBCs, although it was more prevalent in the TME." (PMID 41542041, 2026). "There were distinct GLP-1R expression patterns between tumor cells and the TME." (PMID 41542041, 2026). "In TNBC, GLP-1R is present in immune and tumor cell compartments." (PMID 41542041, 2026). "Both insulin-producing and GLP-1R-producing cells show clustering, and we find clonal expansion, which may give a greatly increased number of such cells in parts of the tumours." (PMID 41488993, 2026). "Another explanation of clustering may be that in some parts of the tumour, the local structure could facilitate expression of GLP-1R." (PMID 41488993, 2026). "Six tumours show cells containing GLP-1R, also with clustering." (PMID 41488993, 2026). "There was a discordance in GLP-1R expression between tumor cells and the TME." (PMID 41542041, 2026). "We more carefully determined the balance of GLP-1R in various tumor cell types." (PMID 41542041, 2026). "Activation of glucagon-like peptide-1 receptor (GLP-1R) could affect cancer treatment responses through direct action in tumor or immune cells." (PMID 41542041, 2026). "Moreover, in the TCGA cohort, almost half of the tumours produce GLP-1R transcripts, and patients with the highest number of transcripts show longer disease-free survival." (PMID 41488993, 2026).
tumor (continued). "However, we found that GLP-1R antagonism enhanced CAR T cell anti-tumor activity, possibly due to differences in the models used." (PMID 40107240, 2025). "For instance, tumours with high GLP-1R expression or those characterized by dysregulation of insulin/IGF signalling pathways may represent more responsive targets." (PMID 41300804, 2025). "In addition to their role in tumor biology, GLP-1R agonists have shown potential cardioprotective effects, particularly in mitigating chemotherapy-induced cardiotoxicity." (PMID 39777709, 2025). "Taken together, the results emphasize the complexity of GLP-1R signaling across different cancer types and suggest that the effects of GLP-1 receptor activation may vary widely depending on the specific tumor biology." (PMID 39777709, 2025). "Elderly patients may experience differential responses to GLP-1R agonists due to age-related changes in GLP1R expression, tumor microenvironment, and systemic physiology." (PMID 39777709, 2025). "Therefore, in preclinical models the effect of GLP-1R therapy should be investigated in studies of early malignant transformation and primary tumor development to better align with current clinical evidence." (PMID 41178720, 2025). "Aberrant activation of PI3K/Akt is commonly observed in various malignancies, and its suppression by GLP-1R agonism suggests a plausible therapeutic mechanism by which tumour progression could be attenuated." (PMID 41300804, 2025). "Emerging studies have highlighted sex-dependent variations in cancer biology and treatment responses, suggesting that GLP-1R agonists could interact differently with tumor progression pathways in male versus female patients." (PMID 39777709, 2025). "Although we found survival benefits among all NEN types after receiving GLP-1Ra therapy in the present study, our findings contrast with select preclinical and clinical studies demonstrating tumor progression in GLP-1R-expressing pancreatic NENs treated with these agents." (PMID 40361517, 2025). "However, the role of GLP-1R agonists in cancer remains complex and not fully understood, particularly across different tumor types." (PMID 39777709, 2025). "Using a comprehensive analysis of gene expression data and survival outcomes a large cohorts of different tumor types, we employed Cox proportional hazards survival analyses, coupled with false discovery rate determinations, to explore correlations between GLP1R expression and survival." (PMID 39777709, 2025). "In the TME, there may be other GLP-1R-expressing cells, like immune cells and fibroblasts, crucial in tumor growth, angiogenesis, and immune responses." (PMID 39908200, 2025). "Additionally, ovarian tissues also exhibited an increase in GLP1R expression in tumor samples compared to normal tissues, although the difference was less pronounced than in the pancreas." (PMID 39777709, 2025). "Second, whether the administration of GLP-1R agonist in mice with DM would result in similar anti-tumor effects on CCA xenografts needs to be examined." (PMID 38877189, 2024). "Thus, the present study aimed to determine the clinicopathological significance of GLP-1R in CCA using tumor tissues from patients in Ov-endemic regions and to investigate the roles of liraglutide, a GLP-1R agonist widely used in patients with DM." (PMID 38877189, 2024). "Their research showed a noticeable drop in GLP1R levels in EC cells, suggesting that the tumor-suppressive role of GLP1R in EC may be mediated through the cAMP/PKA pathway." (PMID 39429275, 2024). "Downregulating GLP-1R in xenografted tumors might also result in tumor growth suppression and induction of iCCA cell death." (PMID 38877189, 2024). "The effects of liraglutide on reduced iCCA cell migration in vitro and reduced tumor growth in vivo might be, nonetheless, independent from the reduction of GLP-1R and directly affecting the intracellular signaling pathways." (PMID 38877189, 2024).
tumor (continued). "Moreover, tumor size and mass were reduced after the introduction of GLP1R overexpression vector, while they were increased following the introduction of si-PKA." (PMID 39429275, 2024). "Thus, the mean H-score (H = 143) was used as the cut-off point for high or low expression of GLP-1R in iCCA tumor tissues." (PMID 38877189, 2024). "The lack of GLP-1R expression was associated with impaired overall survival, larger tumour diameter, higher Ki-67 PI and weaker insulin staining." (PMID 37894845, 2023). "All but four tumours showed at least weak expression of GLP-1R." (PMID 37894845, 2023). "In vivo results of a biodistribution in GLP-1R overexpressing tumour bearing mice at 24 h post-injection demonstrated a significant reduction (at least 57%) of renal retention of all 111In-labeled exendin-4 compounds equipped with a cleavable linker compared to the reference compound." (PMID 37665477, 2023). "All GLP-1R-negative and most (69%) GLP-1R-positive tumours expressed SSTR2 subtype (p = 0.244)." (PMID 37894845, 2023). "It is worth noting that regarding chronic HCC treatment, Ex-4 did not allow tumor cell regrowth by preventing some resistance mechanisms that the cells can acquire, while it exhibited greater capability to inhibit tumor proliferation than liraglutide, another GLP-1R analogue." (PMID 36230573, 2022). "Consistent with a role for NTS GLP-1R signaling in mediating the nausea outcomes induced by this system, GLP-1R blockade attenuates anorexia and weight loss when infused into the NTS of tumor-bearing rats, and reduces pica induced by icv infusion in cisplatin-treated rats treated." (PMID 33803053, 2021). "GLP1R is reportedly overexpressed in many tumour cell types." (PMID 34572888, 2021). "In consequence, radioligands targeting GLP-1R+ tumor lesions with reduced kidney uptake and/or enhanced renal excretion could not be generated." (PMID 34432147, 2021). "Similarly, GLP1R was reduced 51‐fold in the tumour‐bearing mice and increased 71‐fold in ACVR2B/Fc‐treated HCT116 hosts." (PMID 33200567, 2020). "At the start of the survival experiment, the sizes of the subcutaneous GLP-1R tumors were very variable, although mean tumor sizes were similar between the groups (161 ± 205 mm3 [range, 35–657 mm3] in the exendin-4-IRDye700DX group and 171 ± 144 mm3 [range, 36–480 mm3] in the control group." (PMID 32385165, 2020). "The [Nle14,125I-Tyr40NH2]Ex-4 agonist, in contrast, showed excellent tumor uptake and at the same time exhibited pharmacokinetics superior to all other GLP-1R tracers presently available, with particularly high tumor-to-kidney ratio and good contrast to normal organs." (PMID 28103285, 2017). "Thus, the reduced uptake of the radiopeptide, which is observed upon the treatment of mice with vatalanib, is not due to a direct effect of vatalanib on the expression of the GLP-1R but rather to a reduced delivery of the compound to the tumor cells." (PMID 24528513, 2014). "Retained activity in GLP-1R-positive tissue in 68Ga-Ex4NOD12- and 68Ga-Ex4NOD40-injected mice are similar, while that in 68Ga-Ex4NOD27-injected mice shows lower accumulation in some time points in the tumour and the lung." (PMID 25006548, 2014). "For example, GLP-1R agonists have been associated to increased cAMP production and thyroid C-cell proliferation and tumor formation in rodents but not in primates, including humans." (PMID 23990978, 2013). "Increased GLP-1R levels might induce less aggressive tumours." (PMID 41488993, 2026). "Both the number of cells containing insulin or GLP-1R, as well as their appearance in clusters, may occur more frequently than our data describe, because there may be clonal expansions in other parts of the tumours than those we have investigated." (PMID 41488993, 2026). "Thus, in most of the tumours, relatively few tumour cells contain insulin or GLP-1R." (PMID 41488993, 2026).
tumor (continued). "These include the role of GLP-1R in regulating fibroblast growth factor 21 (FGF21) synthesis, which has been implicated in cancer biology, as well as its anti-inflammatory effects, which could suppress tumor-promoting inflammation." (PMID 39777709, 2025). "Additionally, the observed synergy between GLP-1R activation and autophagy/mitophagy pathways may vary across patient-specific factors and tumor microenvironments." (PMID 40107240, 2025). "Thus, GLP-1R expression could be a useful biomarker in estimating the metastatic potential of the tumour and the prognosis of surgically treated patients." (PMID 37894845, 2023). "Moreover, we showed an association between the lack of GLP-1R expression and a larger tumour diameter and weaker insulin staining." (PMID 37894845, 2023). "As Glp1r expression was undetectable in tumors and surrounding non-tumorous tissue in GAN DIO-NASH-HCC mice, this rules out any potential intratumor GLP1R-associated effects of semaglutide, rendering it most likely that semaglutide lowered tumor burden by improving whole-body metabolism." (PMID 38155202, 2023). "The lack of GLP-1R expression was associated with a larger tumour diameter and a higher Ki-67 PI." (PMID 37894845, 2023). "However, the role of GLP1R overexpression in neoplasia remains unknown Incretin mimetic drugs such as exenatide and liraglutide are powerful and widely used treatments for type II diabetes." (PMID 34572888, 2021). "Moreover, GLP1R has shown to be essential for HR control in mice, and thus, its severe down‐regulation in tumour hosts in this study may be responsible in part for cardiac dysfunction." (PMID 33200567, 2020). "GLP-1R overexpression might persist or fade gradually during later tumor progression." (PMID 29335487, 2018). "Similar to GLP1R, GCG expression was significantly decreased in tumor tissues compared to normal tissues (p = 2.47e-03), with a more pronounced reduction in metastatic tissues (p = 5.57e-09)." (PMID 39777709, 2025). "Related studies have demonstrated that GLP-1R activation upregulates in situ expression of fibroblast growth factor-7 (FGF7) in intestinal tumor cells, promoting tumor progression and inducing intestinal hyperplasia." (PMID 40140925, 2025). "First, we have analyzed the gene expression levels of GLP1R and GCG across various normal and tumor tissues." (PMID 39777709, 2025). "To examine the impact of affinity, we selected two series of compounds in this size range against a tumor antigen, HER2, and an endocrine pancreas target, GLP-1R, and compared experimentally measured versus predicted uptake." (PMID 27147293, 2016). "Whereas 70% showed no GLP-1R expression in tumor cells (score 0), there was 29% with weak to moderate positivity (score 1), and only 1% demonstrated strong, clustered membranous staining (score 2)." (PMID 41542041, 2026). "Notably, GLP-1R expression has been documented in certain NENs, particularly pancreatic NETs, raising questions about the potential impact of GLP-1Ra therapy on tumor behavior and survival outcomes in this patient population." (PMID 40361517, 2025). "The in vivo tumor-suppressive effect of semaglutide remained when NK cells were depleted, but was eliminated upon CD8+ cell depletion, suggesting a role for adaptive immune cells in mediating the effect of GLP-1R activation." (PMID 41178720, 2025). "Recently, the use of gelofusine in connection with the glucagon-like peptide 1 receptor (GLP-1R) ligand 111In-DOTA-exendin-4 resulted in a reduced renal retention by 18% in patients without lowering the tumor uptake." (PMID 38717591, 2024). "The median Ki-67 PI of GLP-1R-negative vs. positive tumours was 1.8% (range 0.4–16.1) vs. 0.4% (range 0.1–4.6), respectively, p = 0.022." (PMID 37894845, 2023).
tumor (continued). "SSTR1 was expressed in three (75%), SSTR3 in two (50%), SSTR4 in 0% and SSTR5 in 0% of the GLP-1R-negative tumours, compared to eleven (23%) (p = 0.055), fifteen (31%) (p = 0.589), 0% and three (6%) (p = 1.000) in GLP-1R-positive tumours, respectively." (PMID 37894845, 2023). "Interestingly, PDT with exendin-4 coupled to the photosensitizer IRDye700DX was recently reported to repress tumor growth and improve median survival in BALB/c nude mice bearing GLP-1R expressing tumors." (PMID 37242457, 2023). "Insulin release from a clonal expansion, with or without GLP-1R stimulation, might cause hypoglycaemia, and increased levels of GLP-1R might induce less aggressive tumours." (PMID 41488993, 2026). "Patients with thyroid nodules or cancer were not excluded before beginning GLP-1R therapy, which might influence tumor diagnosis in patients after treatment." (PMID 41178720, 2025). "Reubi & Waser (2003) assessed GLP-1R in different tumor and non-neoplastic tissue." (PMID 31951592, 2020). "Additionally, 68Ga-Ex4NOD12 shows the lowest non-specific uptake tissue not expressing GLP-1R as well as in the blocking experiments (tumour p < 0.04, lung p < 0.003)." (PMID 25006548, 2014). "Notably, WM-CR mice exhibited identical tumor onset and similar progression to SEMA, which supports that weight loss alone may be beneficial independent of GLP1R agonism." (PMID 40094000, 2025). "The difference in insulin staining between the tumours expressing GLP-1R and those lacking GLP-1R expression was statistically significant (p < 0.002)." (PMID 37894845, 2023). "Importantly, even in patients with negative cross-sectional imaging despite the use of GLP-1R PET/CT and ambiguous preoperative tumour localisation, minimally invasive resection with IOUS is feasible, effective, and safe." (PMID 41375058, 2025).